TARDBP (TAR DNA binding protein)
Diseases named in the same sentence as TARDBP in open-access papers (continued):
Sharing a sentence is not in itself a finding about the gene and the disease.
motor neuron disease (128 papers, 2008 to 2026). "Abnormal aggregation of TAR DNA‐binding protein 43 (TDP‐43) is a pathological hallmark of motor neuron disease (MND), yet current methods for quantifying these aggregates in biological samples remain limited in sensitivity and resolution." (PMID 40985163, 2025). "Transactive response DNA binding protein-43 (TDP-43), encoded by TARDBP gene in the human genome, has been identified as a major component for the pathology of motor neuron diseases and related neurodegenerative diseases." (PMID 36968586, 2023). "Most of the mutations that affect the gene that encodes TDP-43 are usually associated with cases of motor neuron disease (MND); however, cognitive disorders (bvFTD and svPPA) have been described in two patients with MND with a mutation in the TARDBP gene." (PMID 37891841, 2023). "SG component proteins with a causal role for motor neuron diseases include TDP-43 (gene symbol TARDBP), FUS, ATXN2, SMN, Tau (gene symbol MAPT), HNRNPA2B1, and HNRNPA1." (PMID 24659297, 2014). "Furthermore, the existence of TARDBP mutations in autosomal dominant ALS with demonstrable TDP-43 pathology strengthens the evidence for a causal role of TDP-43 in inherited forms of motor neuron disease." (PMID 18957104, 2008). "It is characterized by the accumulation of hyper-phosphorylated and ubiquitinated TAR DNA-binding protein 43 (TDP-43) deposits in the brain and spinal cord of patients with this motor neuron disease." (PMID 34943020, 2021). "Mutations in RNA binding proteins such as Tar DNA binding protein-43 (TDP-43), Fused in sarcoma (FUS), survival of motor neuron (SMN1), ataxin-2 (ATX2), optineurin (OPT) and angiogenenin (ANG) all cause motor neuron diseases." (PMID 23164372, 2012). "Among the catalogued ALS-like motor neuron diseases, mutations in SOD1 (ALS1), FUS/TLS (ALS6), VAPB (ALS8), ANG (ALS9), TARDBP (ALS10), FIG4 (ALS11) and a hexanucleotide-repeat expansion (GGGGCC) in the C9ORF72 cause adult onset neurodegenerative disorder." (PMID 22384259, 2012). "Hipk also modifies the levels of an important nuclear protein, TBPH, the fly orthologue of TAR DNA-binding protein 43 (TDP-43), which may have relevance for understanding motor neuron diseases." (PMID 32187190, 2020). "The precise mechanisms of Golgi fragmentation in degenerating motor neurons are not fully understood but first insights arise from studies in animal and cellular models of ALS and related motor neuron diseases linked to mutations in SOD1, Dynein/Dynactin, TARDBP (TDP-43), and VAP-B." (PMID 26696811, 2015). "Abnormalities in the nuclear pore complex have recently been described in ALS, and these defects may contribute to the abnormal subcellular localization of specific proteins linked to motor neuron diseases, such as fused in sarcoma (FUS), TAR DNA-binding protein 43 (TDP-43) and AR." (PMID 28087734, 2017). "This is supported by the identification of trans-activation response element (TAR) DNA binding protein-43 (TDP-43), encoded by TARDBP gene, as the major pathological protein in the inclusions of FTLD-U (hereinafter FTLD-TDP) with or without motor neuron disease, and in sALS." (PMID 33421065, 2021). "Wild-type FUS could rescue the Tardbp knockdown phenotype, but not vice versa, suggesting that TARDBP is upstream of FUS in this pathway responsible for motor neuron disorder." (PMID 21829392, 2011).
Cognitive impairment (123 papers, 2011 to 2026). Abnormal cognition is characterized by deficits in thinking, reasoning, or remembering. "In contrast to fALS associated with variants in e.g. C9ORF72, FUS, or TARDBP, there is hardly any cognitive impairment in SOD1-associated ALS70." (PMID 39366938, 2024). "Our findings are relevant both clinically, considering the effect of cognitive impairment on patients' decision-making and caregivers' burden, and in designing clinical trials for the treatment of patients carrying TARDBP pathogenetic variants." (PMID 38261982, 2024). "Future postmortem studies that determine the central nervous system pathology (eg, TAR DNA-binding protein 43, tau, β-amyloid deposition) underlying the motor neuron deficits and the cognitive impairment may resolve the nature of this overlap with other neurodegenerative diseases." (PMID 34459874, 2021). "We note that the primary underlying pathology contributing to cognitive impairment in probable DLB patients is α-synuclein, with additional β-amyloid, NFT-tau, and possibly other pathologies, such as vascular disease or TAR DNA-binding protein-43." (PMID 31790563, 2019). "While mutations in the TDP-43 gene (TARDBP) are usually associated with ALS, many clinical reports have linked these mutations to cognitive impairments and/or FTD, but also to other neurodegenerative disorders including Parkinsonism (PD) or progressive supranuclear palsy (PSP)." (PMID 38367882, 2024). "Although the patient was diagnosed with familial ALS carrying the variant in TARDBP, her symptom exhibited very slow progression without any cognitive deficit (progression rate = 0.08)." (PMID 37914747, 2023). "TARDBP-ALS patients were significantly more impaired than controls in most examined domains but do not show any specific pattern of cognitive impairment compared with WT-ALS." (PMID 38261982, 2024). "Most TARDBP mutations present with a typical ALS phenotype and no cognitive impairment." (PMID 37333000, 2023).
Lewy body disease (114 papers, 2008 to 2026). "α-synuclein inclusions, known as Lewy bodies, are found in PD and Lewy body dementias, while mutant huntingtin (mHTT) aggregates are formed in HD, and TAR DNA-binding protein 43 (TDP-43) aggregates are found in ALS and FTD brains." (PMID 33122983, 2020). "Finally, the effect of coexistent pathologies—Lewy body disease and TAR DNA-binding protein 43 (TDP-43)—on cortical microstructure was assessed." (PMID 37794477, 2023). "Mediation analyses were conducted to assess the indirect association of APOE-ε4 with cognition through AD-pathology, lacunar infarcts, hyaline arteriosclerosis, cerebral amyloid angiopathy (CAA), Lewy body disease (LBD), and TAR DNA-binding protein 43 (TDP-43)." (PMID 38115150, 2023). "In addition, APOE is related to non-AD neuropathological alterations, such as Lewy body dementia (LBD) characterized by aggregates of the α-synuclein protein and limbic-predominant age-related TAR DNA-binding protein 43 (TDP-43) encephalopathy." (PMID 38115150, 2023).
Huntington disease (110 papers, 2012 to 2026). Huntington disease (HD) is a rare neurodegenerative disorder of the central nervous system characterized by unwanted choreatic movements, behavioral and psychiatric disturbances and dementia. "Inefficient microtubule-based transport in axons is linked with several age-related neurodegenerative diseases including Alzheimer’s, Huntington’s disease, and hereditary spastic paraplegia, as well as with ALS caused by mutations in SOD1, TARDBP, and FUS." (PMID 33837088, 2021). "Mitochondrial transport deficits are linked with several neurodegenerative disorders, such as Alzheimer’s and Huntington’s disease, hereditary spastic paraplegia, Charcot–Marie–Tooth disease, as well as ALS with SOD1, TARDBP, and FUS mutations, and ALS with hexanucleotide repeats in C9orf72." (PMID 38363426, 2024). "NDDs all show accumulation of abnormally folded proteins, including β-amyloid (Aβ) and Tau in AD, α-synuclein (α-syn) in PD, TAR DNA-binding protein 43 (TDP-43) in ALS and huntingtin in Huntington’s disease (HD)." (PMID 38632601, 2024).
cognitive decline (82 papers, 2010 to 2026). "Abnormal protein accumulations, including TAR DNA-binding protein 43 (TDP-43) and tau, contribute to neuronal loss and cognitive decline." (PMID 39728746, 2024). "Together with this core variable set, either MIR132, beta-amyloid, TAR DNA binding protein 43 (TDP-43), IGFBP5, or histone coacetylation modules could explain the mediation of AD-PRS to cognitive decline." (PMID 30349450, 2018).
liposarcoma (64 papers, 2009 to 2025). A usually painless malignant tumor that arises from adipose tissue. "Many gene mutations are responsible for causing familial ALS such as mutations in PFN1, FUS/TLS (fused in sarcoma/translocation in liposarcoma), TARDBP or TDP-43 (TAR-DNA-binding protein 43), UBQLN2, C9ORF72, SOD1 (superoxide dismutase 1), HNRNPA1, OPTN, and VCP." (PMID 27878120, 2016). "Recent evidence also shows that aggregation-related mutations in the RBPs Tar DNA-binding protein 43 TDP-43 and Translocated in liposarcoma protein FUS are associated with the formation of RNA granules that are phase separated, non-membrane-bound ribonucleoprotein aggregates." (PMID 26673865, 2015). "At present, the four major ALS-associated genes are the chromosome 9 open reading frame 72 (C9ORF72), Cu-Zn superoxide dismutase 1 (SOD1), TAR DNA-binding protein 43 (TARDBP), and fusion in malignant liposarcoma/translocation in liposarcoma (FUS/TLS), in addition to at least other 40 genes." (PMID 32487123, 2020). "Mutations in several genes are causative for FALS, including fused in sarcoma/translated in liposarcoma (FUS), superoxide dismutase-1 (SOD1), TAR DNA-binding protein (TARDBP), angiogenin (ANG), vesicle-associated membrane protein B (VAPB), optineurin (OPTN), and valosin-containing protein (VCP)." (PMID 23577159, 2013). "Another type of ALS associated genes code for RNA binding proteins that are also involved in RNA processing, including FUS/TLS (translocated in liposarcoma) and TDP-43 (TAR DNA-binding protein 43)." (PMID 33918863, 2021). "The most common genes associated with ALS are chromosome 9 open reading frame 72 (C9orf72), Superoxide dismutase (SOD1), TAR DNA-binding protein 43 (TARDBP), fused in sarcoma/translocated in liposarcoma (FUS/TLS) and matrin-3." (PMID 30175288, 2018). "Notably, DNA/RNA-binding proteins like fused in sarcoma/translated in liposarcoma (FUS/TLS) and TAR DNA-binding protein (TDP)-43 have been pinpointed as the primary etiological factors in the familial forms of the neurodegenerative condition of ALS." (PMID 38348393, 2024).
synucleinopathies (58 papers, 2009 to 2026). "For instance, the accumulation of aggregates of amyloid-beta and tau in AD, alpha-synuclein in PD and other synucleinopathies, and TAR DNA-binding Protein 43 (TDP-43) in ALS has been largely associated with the progressive neurodegeneration and clinical symptoms." (PMID 38766825, 2025). "These comprise beta-amyloid (Aβ) plaques in AD, aggregates of α-synuclein in PD and other synucleinopathies, and inclusions of the TAR DNA-binding protein (TDP)-43 in ALS and frontotemporal disorders (FTD)." (PMID 36674852, 2023). "In conclusion, little is known about the heterogeneous etiology of SNAP, especially with regard to potential contributors that cannot be determined in vivo, such as TAR DNA-binding protein (TDP)-43, often associated with hippocampal sclerosis, α-synucleinopathy, and PART." (PMID 33990226, 2021). "In addition, we know that overlapping pathologies, including α-synucleinopathy and vascular and TAR DNA-binding protein 43 (TDP-43) pathology are present in AD patients." (PMID 37371506, 2023). "Tar-DNA binding protein 43 (TDP-43) and α-synuclein (αS) are two proteins involved in the formation of amyloid deposits observed among several neurodegenerative diseases known as TDP-43 proteinopathies and α-synucleinopathies, respectively." (PMID 38052886, 2023). "Additional polypathologies contribute to clinical progression in AD, including vascular and inflammatory etiologies, α-synucleinopathy and TAR DNA-binding protein-43 (TDP-43) diseases, many of which do not currently have specific in vivo measures." (PMID 35314672, 2022).
Parkinsonism (49 papers, 2008 to 2026). Characteristic neurologic anomaly resulting from degeneration of dopamine-generating cells in the substantia nigra, a region of the midbrain, characterized clinically by shaking, rigidity, slowness of movement and difficulty with walking and gait. "In this study we sequenced exon 6 of TARDBP gene in a large cohort of Italian patients affected by different forms of parkinsonism and identified 4/735 (0.5%) PD and 2/142 (1.4%) atypical parkinsonism cases harboring pathogenic mutations." (PMID 36247987, 2022). "Consistent with evidence indicating a broad role of TDP-43 in neuronal degeneration and with the co-existence of parkinsonism and ALS/FTD in few TARDBP mutation carriers, previous studies were conducted to investigate the role of TARDBP mutations in PD and other parkinsonisms (PSP and CBS)." (PMID 36247987, 2022).
argyrophilic grain disease (45 papers, 2013 to 2025). A tauopathy characterized pathologically by the presence of silver stain positive lesions called argyrophilic grains, oligodendrocytic coiled bodies, and neuronal tau-positive pretangles. "From enrollment, other cause of neurodegenerative disease has been excluded, thus, tau, TAR DNA-binding protein 43 (TDP-43), hippocampal sclerosis, and argyrophilic grain disease might still be the cause of these specific disease group." (PMID 38105274, 2023). "This category comprises several different types of amyloid-unrelated pathologies such as primary age–related tauopathy (PART), hippocampal sclerosis, TAR DNA binding protein (TDP)-43 pathology, argyrophilic grain disease (AGD), and accelerated aging." (PMID 36498962, 2022).
progressive supranuclear palsy (44 papers, 2013 to 2025). A rare late-onset neurodegenerative disease characterized by supranuclear gaze palsy, postural instability, progressive rigidity, and mild dementia. "Distinct biomarker patterns were seen in different FTLD subtypes, with increased NFL and reduced P-tau/T-tau in FTLD–TAR DNA-binding protein 43 and reduced T-tau in progressive supranuclear palsy compared to other FTLD variants." (PMID 35173015, 2022). "A case has been described as a carrier of the TARDBP K263E mutation who developed FTD, progressive supranuclear palsy (PSP), and chorea; furthermore, these symptoms were correlated with the presence of TDP-43 inclusions in the brainstem and subcortical nuclei, both in neurons and glia." (PMID 37891841, 2023). "CBS can arise from several non-AD pathologies, including corticobasal degeneration (CBD), progressive supranuclear palsy (PSP), or TAR DNA-binding protein 43 (TDP-43) proteinopathy, or can occur as a coexisting pathology." (PMID 40314736, 2025).
motor neuron degeneration (43 papers, 2008 to 2025). "Such efforts would aim to replicate the primary hallmarks of familial and sporadic ALS at molecular (e.g., TARDBP/TDP43 aggregation), cellular (e.g., motor neuron degeneration), and physiological levels (manifesting muscle weakness and shortened lifespan)." (PMID 40307231, 2025). "Four major genes have been identified as causative of motor neuron degeneration: C9orf72 (Chromosome 9 open reading frame 72), SOD1 (Cu2+/Zn2+ superoxide dismutase), TARDBP (TAR DNA binding protein) and FUS (RNA binding protein Fused in Sarcoma)." (PMID 35625004, 2022). "Missense mutations in the gene encoding human TDP-43, TARDBP, have been identified in familial and sporadic ALS, suggesting that TDP-43 dysfunction leads to motor neuron degeneration." (PMID 31345270, 2019). "Does a central pathogenic mechanism involving genetic interactions of FUS and TARDBP lead to motor neuron degeneration in ALS?" (PMID 21829392, 2011). "A recent study demonstrated that ALS patient-derived TARDBP/TDP-43 mutation at the carboxyl-terminal domain (M337V) causes splicing deregulation without motor neuronal degeneration in mice." (PMID 33333804, 2020). "Taken together with previous reports, we conclude that mutations in TARDBP are not a common cause of sporadic motor neuron degeneration." (PMID 18545701, 2008).
amyloid (39 papers, 2013 to 2025). "For example, microglia-specific KO of TAR DNA-binding protein of 43 kDa (TDP-43) enhanced the phagocytosis of amyloid plaques, but it also increased the phagocytosis of synapses." (PMID 34072424, 2021). "Staining for fused-in-sarcoma (FUS) and TAR DNA-binding protein 43 (TDP-43) proteins was negative, and no amyloid plaques were observed; tau pathology was scarce." (PMID 30935398, 2019).
cerebrovascular disease (34 papers, 2015 to 2025). "We further assessed the impact of medical comorbidities and common co-existing pathologies in the aging brain, including cerebrovascular disease and TAR DNA binding protein 43 (TDP-43), on plasma p-tau levels." (PMID 36575455, 2022). "Clinico‐pathological studies have shown that 80% of older adults with probable AD have mixed pathologies, often with a combination of AD, cerebrovascular disease, Lewy body pathology, and TAR DNA‐binding protein 43 (TDP‐43) proteinopathy." (PMID 40760693, 2025). "There were no phospho-TAR DNA-binding protein 43-positive inclusions or other pathology such as cerebrovascular disorders." (PMID 35931783, 2022). "Lastly, lack of other biomarkers, including cerebrovascular disease, α-synuclein, TAR DNA-binding protein 43 (TDP-43), or Lewy body, should be considered due to the fact that those contribute to neurodegenerations." (PMID 35995824, 2022).
semantic dementia (34 papers, 2010 to 2026). "Of note, a significant proportion of FTD patients with a TARDBP mutation were found to fulfill criteria for semantic dementia by other reports." (PMID 35911889, 2022). "In Brazil, Machado-Costa identified a TARDBP mutation in a 54-year-old patient diagnosed with semantic dementia." (PMID 34248820, 2021). "Semantic dementia, including the semantic variant of primary progressive aphasia (svPPA), is strongly associated with TAR-DNA binding protein 43 (TDP-43) type C pathology." (PMID 28912300, 2018). "CSF-Progranulin levels were significantly lower in FTD type patients with semantic dementia and behavioral variant FTD mainly attributed to the Tar-DNA-Binding-Protein (TDP) 43 compared to predominantly Tau-mediated PNFA (p < 0.05)." (PMID 30013506, 2018). "We compared the expression of ASRGL1 and TARDBP between ALS individuals and controls (frontotemporal lobe dementia (FTLD) and non-neurological cases) in different subtypes of neurons and glia, in motor cortex (BA4) and in dorsolateral prefrontal cortex (BA9), as a control region." (PMID 38755145, 2024).
cerebral amyloid angiopathy (31 papers, 2014 to 2025). "Other pathologies, such as cerebral amyloid angiopathy, hippocampal sclerosis, argyrophilic grains, and TAR DNA-binding protein 43, have been studied less and their roles remain unclear." (PMID 35002917, 2021). "Finally, we assessed the sensitivity of the biomarkers for the presence of common non-AD pathologies at autopsy, including cerebral amyloid angiopathy (CAA), Lewy body (LB) pathology, and limbic TAR DNA-binding protein 43 (TDP-43) pathology." (PMID 34266917, 2021).
Brain atrophy (30 papers, 2015 to 2025). Partial or complete wasting (loss) of brain tissue that was once present. "TAR DNA-binding protein 43 (TDP-43) inclusions are known to accelerate brain atrophy and mainly affect the amygdala (Stage 1) and the hippocampus (Stage 2)." (PMID 35592489, 2022). "On the other hand, lack of TARDBP/TDP-43 in the forebrains of mice resulted in age-dependent brain atrophy by downregulating protein Tbc1d1 in skeletal muscles, leading to compromised neuronal function." (PMID 33333804, 2020).
inclusion body myositis (30 papers, 2012 to 2025). A slowly progressive degenerative inflammatory disorder of skeletal muscles characterized by late onset weakness of specific muscles and distinctive histopathological features. "TDP-43 (TAR DNA-binding protein 43), which is associated with neurodegenerative disorders, inclusion body myositis and rimmed vacuole myopathies, regulates alternative splicing as well as mRNA trafficking and translation and mRNP granule formation." (PMID 34685485, 2021).